CDK4 (cyclin dependent kinase 4)
Diseases named in the same sentence as CDK4 in open-access papers (continued):
Sharing a sentence is not in itself a finding about the gene and the disease.
breast cancer (continued). "A series of CDK4/6 inhibitors have recently emerged for the treatment of late-stage ER+ breast cancer patients that are particularly effective when used in conjunction with hormone therapy." (PMID 32374727, 2020). "Targeting PI3K in CDK4/6-resistant breast cancer cells appears to be effective in both PIK3CA mutant and wild-type models, whereas targeting mTORC1 is effective in PIK3CA wild-type xenograft and one of two PIK3CA-mutant models." (PMID 32795346, 2020). "In contrast, the proliferation marker cyclin D1/2 was even reduced at higher concentrations in all 3 cell lines and CDK4 in the two breast cancer cell lines whereas PCNA levels stayed unaffected." (PMID 32292575, 2020). "An ER+ breast cancer model with targeted RB1 deletion was used to identify signatures of CDK4/6 activity and RB-dependency (CDK4/6-RB integrated signature)." (PMID 32242058, 2020). "Insights into the biological consequences of CDK inhibition in specific tumor types have led to the successful development of CDK4/6 inhibitors as treatments for certain types of breast cancer." (PMID 32645016, 2020). "Since previous studies have shown that the RB gene plays an important role in the mechanism of CDK4/6 inhibitors, we detected the mRNA levels of RB in different breast cancer cell lines." (PMID 33061853, 2020). "Altogether, these results demonstrate that the phosphorylation of Ser26-USP51 is critical for CDK4/6-mediated breast cancer metastasis in vivo." (PMID 32296027, 2020). "The eventual progression of HR-positive breast cancer, even after treatment with CDK4/6 inhibitors, has limited the success of this therapy in the clinic, emphasizing the need to identify mechanisms of this acquired resistance." (PMID 33260316, 2020). "The activity of cyclin D and CDK4/6 complexes is considered to play the major role in tumor cell proliferation driven by estrogen, especially in breast cancer." (PMID 33364954, 2020). "Several studies demonstrated that CDK4/6 inhibitors were not only efficacious for advanced or metastatic breast cancer patients but also showed promise for early breast cancer patients." (PMID 32933570, 2020). "To analyze potential causative effects, we investigated the behavior of the breast cancer bootstrap genes in MCF7 cells treated with palbociclib and found the directionality was consistent with the suppression of CDK4/6 activity." (PMID 32242058, 2020). "In fact, during the G0-to-S phase progression, an elevated expression of c-myc elicited a shortened G1 phase by activating the CDK4/6 activity, thus inducing palbociclib resistance in breast cancer." (PMID 32934206, 2020). "The use of autophagy inhibitors in combination with CDK4/6i has demonstrated promising synergy in multiple cancer types, such as breast cancer, gastric cancer, and PDAC13,21." (PMID 32843618, 2020). "Several recent studies reported that SMAD2 promoted the tumor progression by upregulating the CDK2, CDK4, and cyclin E in metastatic breast cancer cells." (PMID 33330073, 2020). "In summary, LMWE appears to be predictive in sensitivity for the combination of CDK4/CDK6 inhibitors with autophagy targeting in advanced ER+ breast cancer." (PMID 32878084, 2020). "Seventy per cent of all breast cancer cases are oestrogen receptor positive (ER+) and targeted therapies such as endocrine therapy or Cdk4/6 inhibitors are used to treat this clinical subtype, resulting in dramatic improvements in long-term survival rates." (PMID 32842890, 2020). "Recently, the addition of cyclin-dependent kinase 4 and 6 (CDK4/6) inhibitors to endocrine therapy has become the new standard of care for first- and second-line treatment for advanced breast cancer." (PMID 32787886, 2020). "Aberrant activation of cyclin-dependent kinases (CDKs) is strongly correlated with tumor malignancy 10, and CDK4/6 inhibitors (CDK4/6is) have already been approved by the FDA for the treatment of breast cancer." (PMID 32929370, 2020).
breast cancer (continued). "Although our cohort, to the best of our knowledge, is the largest published up to date of metastatic breast cancer patients undergoing concurrent radiotherapy and CDK4/6 inhibitors, numbers are still limited." (PMID 32788596, 2020). "Small-molecule CDK4/6-inhibitors as ribociclib, palbociclib, and abemaciclib have shown the ability to inhibit the growth of ER–positive breast cancer cells, act synergistically with antiestrogens, and reverse endocrine resistance." (PMID 32979150, 2020). "Herein, we demonstrated that specific inhibition of CDK4/6 was able to block tumor metastasis of breast cancer by destabilizing the ZEB1 protein in vitro and in vivo." (PMID 32296027, 2020). "MiR-142-3p suppresses growth of colorectal cancer and breast cancer cells by targeting CDK4, Beach-1, and CDC25C." (PMID 33396321, 2020). "CDK4/CDK6/cyclin D signaling is altered in 35% of ER+ breast cancer patients, but 16% of patients fail to respond to the treatment." (PMID 32878084, 2020). "Palbociclib is a cyclin‐dependent kinase 4/6 inhibitor indicated for treatment of hormone receptor‐positive/human epidermal growth factor receptor 2‐negative advanced breast cancer in combination with endocrine therapy." (PMID 31448513, 2020). "In breast cancer, Abemeciclib inhibits CDK4/6, interrupting the cell cycle and the development of the tumour." (PMID 32640984, 2020). "Despite the proven clinical benefit of adding CDK4/6 inhibitors to endocrine therapy for ER+/HER2− breast cancer, ultimate progression on therapy remains a significant factor impacting long-term benefits of CDK4/6-based therapies." (PMID 32795346, 2020). "Beyond breast cancer, a promising role for CDK4/6 inhibitors has also been observed in other malignancies, including NSCLC, glioblastoma (GBM), melanoma, and colorectal and ovarian cancers, which suggests their potential efficacy across multiple tumor types." (PMID 32296027, 2020). "By sponging miR-206, MALAT1 up-regulates ANXA2 and KRAS expression in gallbladder cancer cells, and reduces CDC42 and up-regulates CDK4 expression in breast cancer cells." (PMID 32174966, 2020). "FGFR aberrant signaling that was observed in ER+ breast cancer patients undergoing treatment with CDK4/6 inhibitors plus estrogen inhibitors represents another mechanism of tumor resistance." (PMID 32210163, 2020). "Treatment paradigms in advanced hormone receptor (HR)-positive breast cancer were substantially transformed with cyclin-dependent kinase 4 and 6 inhibitors (CDK4/6i) approval." (PMID 32882980, 2020). "The potential of simultaneously targeting ER, PI3K/mTOR, and CDK4/6 signaling de novo was evaluated in three ER+/HER2− breast cancer xenograft models representing diverse molecular backgrounds of PI3K/mTOR pathway activation." (PMID 32795346, 2020). "MALAT1 binds miR-1, miR-124, and miR-448, and acts as a ceRNA to reduce CDC42 and up-regulate CDK4 expression, leading to breast cancer cell cycle progression, cell migration, and invasion." (PMID 32174966, 2020). "Dysregulation in cyclin/CDK/Rb pathway is frequent in many type of human cancers, including breast cancer (BC), in which CDK4/6 have been identified as key drivers of proliferation in HR-positive BC." (PMID 32899866, 2020). "More ongoing and recruiting clinical trials are evaluating the efficacy of CDK4/6 inhibitors in other breast cancer subtypes and after the disease has progressed." (PMID 30959874, 2019). "CCND1 stimulates the cell cycle in breast cancer by binding to cyclin-dependent kinase 4/6 (CDK4/6)." (PMID 31112577, 2019). "The CDK4 inhibitor letrozole has been used to successfully treat breast cancer and has recently entered clinical trials for treatment of various diseases." (PMID 32117430, 2019).
breast cancer (continued). "Palbociclib, a selective inhibitor of the cyclin-dependent kinases CDK4/6, has been applied for breast cancer treatment." (PMID 31787897, 2019). "Three CDK4/6 inhibitors have recently received FDA approval for ER + breast cancer, including albociclib (PALBO) (Pfizer, FDA 2015), ribociclib (RIBO) (Novartis, FDA 2017), and abemaciclib (ABE) (Lilly, FDA 2017)." (PMID 31253784, 2019). "Upon pharmacological inhibition of CDK4/6, upregulation of AKT signaling in breast cancer cells is linked to the accumulation of cyclin D130." (PMID 30914635, 2019). "This has led to the successful transition of CDK4/6 inhibitors into the clinic for ER+ breast cancers where it is used in combination with endocrine therapy." (PMID 30720718, 2019). "We have previously used isobologram analysis to confirm synergistic interaction among HER2 and CDK4/6 inhibitors in breast cancers, which serves as a positive control for the identification of synergy by drug-drug ‘checkerboard’ experiments." (PMID 31742555, 2019). "Numerous inhibitors targeting these kinases are available, with some already in clinical use (e.g. the highly specific CDK4 and − 6 inhibitors Palbociclib and Ribociclib for breast cancer patients)." (PMID 30728057, 2019). "The aim of this review is to summarize the molecular background and the latest evidence on the efficacy of CDK4/6 inhibitors for the treatment of breast cancer." (PMID 30959874, 2019). "For example, there is great interest in extending the clinical success of CDK4/6 inhibitors in hormone receptor-positive luminal breast cancer to metastatic HER2+ breast cancer by combination therapy with T-DM1." (PMID 30897808, 2019). "Another study using human breast cancer cells reported that δ-TCT inhibited the cell cycle through the control of Rb/cyclin D/CDK4 pathway, and induced apoptosis." (PMID 30634632, 2019). "In parallel with clinical trials combining CDK4/6 inhibitors to treat HER2+ breast cancer, we sought to prospectively model tumor evolution in response to this regimen in vivo and identify a clinically actionable strategy to combat drug resistance." (PMID 31444334, 2019). "Though recent phase III trials demonstrated a PFS and even an overall survival benefit for CDK4/6 inhibitors for advanced HR+/HER2- breast cancer in the first or second-line setting, there is limited evidence to inform their CNS-specific activity." (PMID 31695840, 2019). "Ongoing trials evaluating the combination of CDK4/6 inhibitors with PIK3CA agents in breast cancer [ClinicalTrials.gov June 2019]." (PMID 31396487, 2019). "Cyclin D1 activates CDK4/6 which is a current target in the clinic for chemoresistant cases of breast cancer." (PMID 31106142, 2019). "Among the clinical studies that investigated the efficacy of CDK4/6 inhibitors in breast cancer, a few also included patients with triple-negative disease." (PMID 30959874, 2019). "Our study evaluated the efficacy of combining CDK4/6 inhibitors with 6 cytotoxic agents widely used for glioblastoma, lung and breast cancers in either concurrent or sequential administration schedules." (PMID 31600301, 2019). "Rb has an important role in the CDK4/6 molecular pathway and consequently also in mediating anti-tumor responses to CDK4/6 inhibitors in breast cancer." (PMID 30959874, 2019). "CDK4/6–cyclin D complex plays a crucial part in breast cancer, with high sensitivity to CDK4/6 inhibitors, such as luminal-type and hormone-resistant cell lines." (PMID 31448056, 2019). "Recent exciting preclinical studies warrant clinical proposition of CDK4/6 inhibitors to patients with HER2+ breast cancer and multiple clinical trials are currently being conducted." (PMID 31444334, 2019). "Administering CDK4/6 for treating breast cancer has been reported to increase TNF-α production and antigen presentation." (PMID 30828336, 2019).
breast cancer (continued). "Our unexpected findings contrast with the initial application of CDK4/6 inhibitors in treating ER+ breast cancers that are often characterized with dysregulated CDK4/6 activation, where the oncogenic addiction to cyclin D1 is being targeted." (PMID 30718512, 2019). "As a notable recent example, this approach was used to identify estrogen receptor (ER)-positive breast cancer as a target disease for the inhibitors of CDK4/6 kinases essential for cell cycle progression in G1." (PMID 31382571, 2019). "While questions regarding efficacy are still awaiting results from ongoing and future randomized trials, these preclinical and clinical results already demonstrate promise for the use of CDK4/6 inhibitors in this subtype of breast cancer." (PMID 30959874, 2019). "Despite the initial success of anti-CDK4/6 agents such as palbociclib in ER+ breast cancers, drug resistance remains a major challenge for a significant subset of patients." (PMID 31100952, 2019). "Rb is usually intact in HR+ breast cancer and is important for the efficacy of CDK4/6-inhibitors in the treatment of breast cancer." (PMID 31058077, 2019). "In both murine models and breast cancer patients, CDK4/6 inhibition induced anti-tumor immunity through suppression of Tregs and contributing to anticancer effects." (PMID 30991686, 2019). "Combinations of CDK4/6 inhibitor with hormonal therapy in patients with HR+ breast cancer enhanced the inhibition of tumor development and progress free survival in clinical trial and have been approved by FDA for the treatment of metastatic HR+ breast cancer." (PMID 31600301, 2019). "Combining CDK4/6 inhibitors with iCPI treatment led to complete tumor regression and immunological memory in an experimental murine breast cancer model suggesting this treatment regimen as a promising option." (PMID 31178856, 2019). "There are three highly selective CDK4/6 inhibitors that have been approved for breast cancer therapy: Palbociclib, Ribociclib and Abemaciclib (ABC) (Verzenio®)." (PMID 30800400, 2019). "It was the first of a series of CDK4/6 inhibitors, whose anti-cancer potency was proved for breast cancer cells." (PMID 30959874, 2019). "Combination of CDK4/6 inhibitor and anti-PD-1 immunotherapy enhanced tumor regression and dramatically improved OS rates in mouse breast cancer models." (PMID 30991686, 2019). "Taken together, these results demonstrate that ivermectin treatment of canine mammary tumor cells triggers accumulation of cells in the G1 phase via the inactivation of cyclin D1 and CDK4." (PMID 31375107, 2019). "Several clinical trials are assessing CDK4/6 inhibition across breast cancers, allowing for future assessment of applicability in BLBC." (PMID 30720718, 2019). "The loss of FAT1 also contributes to the mechanism of resistance mediated by CDK4/6i in ER+ breast cancer." (PMID 31822636, 2019). "In this study, we investigated the mechanism of CDK4/6 inhibitor resistance and variation after CDK4/6 inhibitor resistance using breast cancer cell lines, hormone-resistant cell lines, and two different kinds of CDK4/6 inhibitor resistance cell lines." (PMID 31448056, 2019). "Selective inhibition of CDK4/6 is now standard-of-care therapy for ER+ breast cancer, with concerted efforts underway to extend this therapy to other breast cancer subtypes, including TNBC." (PMID 31100952, 2019). "Treatment of late-stage ER+ breast cancer patients with CDK4/6 inhibitors in combination with endocrine therapy has been tremendously successful." (PMID 31106278, 2019). "We demonstrate that breast cancer tumor cells continue to rely on ER signaling to drive tumor growth despite exposure to CDK4/6i inhibitors." (PMID 31852484, 2019). "To date, the largest study evaluating CDK4/6 inhibition as novel targeted therapy for patients with HER2-positive advanced breast cancer was published three years ago." (PMID 30959874, 2019).
breast cancer (continued). "Our results demonstrate that low Pxn phosphorylation levels at Ser 83, consequent to the reduced CD1/Cdk4 functional interaction, led to inhibition of Rac1-activity, as evidenced by the decrease of pSer144-Pak1 levels, in all breast cancer cell lines tested." (PMID 31426542, 2019). "There are now three US FDA approved CDK4/6 inhibitors for breast cancer, Palbociclib (IBRANCE®, Pfizer Inc.), ribociclib (Kisqali®, Novartis Pharmaceuticals Corporation), and abemaciclib (VERZENIOTM, Eli Lilly and Company)." (PMID 31480474, 2019). "This supports our preclinical observations that ER signaling, and ER-mediated breast cancer cell growth, is maintained in a post-CDK4/6i setting and warrants the evaluation of elacestrant in patients after disease progression on a CDK4/6 inhibitor." (PMID 31852484, 2019). "We demonstrate in preclinical cell line and patient-derived xenograft models that ER signaling mediated breast cancer cell growth is maintained in most settings despite de novo or acquired resistance to CDK4/6 inhibitors." (PMID 31852484, 2019). "In contrast to SMARCA4-proficient ovarian controls, SCCOHT and ER+ breast cancer cell lines retain RB and express lower levels of the CDK4/6 inhibitor p16INK4a, a profile that has been associated with positive responses to palbociclib." (PMID 30718512, 2019). "Palbociclib has been recently approved for the treatment of advanced breast cancer, targeting CDK4 and CDK618." (PMID 31101827, 2019). "Combinations of CDK4/6 inhibitors and anti-hormonal therapy have demonstrated significant efficacy against HR-positive breast cancer." (PMID 31600301, 2019). "Currently, a number of clinical phase II and phase III studies are ongoing to evaluate the clinical benefit of combining HER2-targeted approaches with CDK4/6 inhibitors for treating HER2-positive advanced breast cancer." (PMID 30959874, 2019). "Our data are consistent with an onco-suppressor model in which OHPg/PR-B act as novel inhibitors of CD1/Cdk4, thus promoting the mesenchymal-epithelial transition and the reduction of breast cancer cell aggressiveness." (PMID 31426542, 2019). "Based on these results, we propose FGFR1 inhibitors in combination with ER and CDK4/6 antagonists as a testable therapeutic strategy in ER+ breast cancers also harboring aberrant FGFR signaling as a result of FGFR pathway gene alterations." (PMID 30914635, 2019). "Because the cost of treatment for metastatic breast cancer is often very high, especially some new drugs, such as targeted drugs, CDK4/6 inhibitors, PD1/PD-L1 inhibitors, etc." (PMID 31829978, 2019). "In a pivotal study of the CDK4/6 inhibitor palbociclib, Finn and colleagues compared baseline gene expression profiles from breast cancer cell lines highly sensitive or resistant to palbociclib." (PMID 30018827, 2018). "Twenty-one of the well established breast cancer biomarkers, including CDK4 and MTOR were unaffected by fat tissue in our sequencing data." (PMID 30190792, 2018). "Combined endocrine treatment with a CDK4/6 inhibitor is now the standard of care in either first- or second-line treatment of metastatic ER+ breast cancer." (PMID 30489256, 2018). "These three studies established CDK4/6 inhibitors as an important class of drugs in the treatment of metastatic HR-positive/HER2-negative breast cancer." (PMID 29218462, 2018). "In view of the recent progress in treatment of estrogen-receptor positive breast cancers, a series of trials is evaluating addition of CDK4/6 inhibitors, aromatase inhibitors or fulvestrant to HER2-targeted and cytotoxic chemotherapy in TPBC patients." (PMID 29670855, 2018). "Clinically, dinaciclib has displayed significant toxicity in a phase I trial, while the FDA-approved CDK4/6 selective inhibitor abemaciclib has shown remarkable efficacy in safely treating ER+/HER2–/RB1WT breast cancer." (PMID 30185666, 2018). "Activation of cyclin D1 and CDK4/6 plays a significant role in the tumorigenesis of HR+/HER2+ breast cancer." (PMID 30018827, 2018).